NAT2 (N-acetyltransferase 2)
Diseases named in the same sentence as NAT2 in open-access papers (continued):
Sharing a sentence is not in itself a finding about the gene and the disease.
psoriasis (2 papers, 2018 to 2020). An autoimmune condition characterized by red, well-delineated plaques with silvery scales that are usually on the extensor surfaces and scalp. "In this regard, more detailed studies should be carried out in larger populations to demonstrate the relationship between NAT2 gene polymorphisms and psoriasis." (PMID 29992137, 2018). "In this study, we aimed to demonstrate whether the variations in the NAT2 gene lead to a predisposition to psoriasis by affecting the enzyme's ability to metabolize drugs and environmental components or not." (PMID 29992137, 2018). "In that case, can NAT2 gene acetylation polymorphisms contribute to the pathogenesis of the disease by facilitating the factors that may trigger psoriasis?" (PMID 29992137, 2018). "In the current study, we also aimed to assess whether the NAT2 polymorphisms have any effect on the clinical characteristics of psoriasis (such as the age of the disease onset and the severity of the disease)." (PMID 29992137, 2018). "In conclusion, rs1799929, rs1799930, and rs1799931 polymorphisms of the NAT-2 gene do not appear to be a risk factor for the development of psoriasis." (PMID 29992137, 2018). "In the present study, we investigated whether the most common three polymorphisms (481C>T, 590G>A, and 857G>A), effective in the acetylation phenotype of the NAT2 gene, have any effect on the development and clinical features of psoriasis vulgaris, i.e., the most common clinical type of psoriasis." (PMID 29992137, 2018). "Even though our findings indicated that NAT2 polymorphisms are not directly related to the pathogenesis of psoriasis, these polymorphisms may play a role in the age of onset and severity of the disease." (PMID 29992137, 2018).
rectal cancer (2 papers, 2010 to 2015). A primary or metastatic malignant neoplasm that affects the rectum. "Furthermore, as observed in other phase II metabolizing enzyme polymorphisms, NAT2 genetic variants have been used as a genetic marker in different diseases like bladder and colon-rectal cancers (fast acetylator and slow acetylator, respectively)." (PMID 20923563, 2010).
resistant hypertension (2 papers, 2021 to 2025). "In a previous work, the pharmacokinetics of oral HLZ were found to be dependent on the NAT2 genotype during pregnancy, and SA status was shown to be associated with clinical blood pressure and 24-h blood pressure after HLZ treatment in patients with resistant hypertension." (PMID 33815485, 2021).
rheumatoid arthritis (2 papers, 2018 to 2020). A chronic, systemic autoimmune disorder characterized by inflammation in the synovial membranes and articular surfaces. "NAT2 acetylation polymorphisms have also been studied in rheumatoid arthritis (RA)." (PMID 29992137, 2018).
type 1 diabetes (2 papers, 2014 to 2022). "In addition to rs1495741 (NAT2-acetylator tagging SNP), rs7533564 (Chr1:78,825,912, C < T) was associated with SIF (Skin Intrinsic Fluorescence; a comparable measurement to SAF measured with the SCOUT DS device) in a previous study in type 1 diabetes individuals." (PMID 36536295, 2022).
AIDS (1 paper, 2012). A syndrome resulting from the acquired deficiency of cellular immunity caused by the human immunodeficiency virus (HIV). "Recently, we reported the gain of function alleles *10 and *11 in NAT1 to be protective against SMX-induced hypersensitivity in HIV/AIDS patients, but this was only observed in patients who are slow acetylators for NAT2, a rare example of a gene-gene-drug interaction." (PMID 22824134, 2012). "NAT2 slow acetylator genotype/phenotype was suggested to predispose to SMX hypersensitivity in non-HIV/AIDS individuals, while no such associations were observed in HIV/AIDS patients in several studies, possibly owing to reduced activities of liver drug metabolizing enzymes during HIV infection." (PMID 22824134, 2012).
choroidal neovascularization (1 paper, 2024). An eye disorder described by the growth of new blood vessels that originate from the choroid through a break in the Bruch membrane into the sub–retinal pigment epithelium (sub-RPE) or subretinal space. "The data of NAT2 showed that the incidence of choroidal neovascularization (CNV) in patients with unilateral exudative AMD (unilateral exudative AMD) with high plasma concentrations of DHA and EPA decreased significantly for three consecutive years." (PMID 39119460, 2024).
colon adenoma (1 paper, 2012). An adenoma that arises from the colon. "Individuals with a history of smoking and NAT2 genetic variants who are exposed to cigarette toxins, such as nickel sulphate and benzo(b)fluoranthene, may have a reduced detoxification ability, thus resulting in an increased risk of colon adenoma as well as cancer." (PMID 23226745, 2012). "The underlying mechanisms by which NAT2 polymorphisms affect colon adenomas in individuals with a history of smoking are not fully understood." (PMID 23226745, 2012).
COVID-19 (1 paper, 2024). A disease caused by infection with severe acute respiratory syndrome coronavirus 2. "Besides, our list also included 23 star-alleles of the Cytochrome P450 (CYP) superfamily, the NAT2 gene, and 11 HLA alleles have been reported to be associated with differential responses to drugs used for COVID-19 treatment at different levels." (PMID 38509882, 2024).
esophageal cancer (1 paper, 2014). A primary or metastatic malignant neoplasm involving the esophagus. "In the esophagus, the slow NAT2 acetylator genotype was more susceptible to esophageal cancer in Japan." (PMID 24586291, 2014). "In a more recent study in India, NAT2 acetylator genotypes did not influence susceptibility to esophageal cancer." (PMID 24586291, 2014). "However, in another study in Taiwan, NAT2 polymorphisms did not affect the risk of esophageal cancer, irrespective of environmental factors." (PMID 24586291, 2014).
essential tremor (1 paper, 2022). A relatively common disorder characterized by a fairly specific pattern of tremors which are most prominent in the upper extremities and neck, inducing titubations of the head. "Our findings were also supported by genetic data, as essential tremor is also associated with the variant N‐acetyltransferase 2 (NAT2) gene." (PMID 35259281, 2022).
glioblastoma (1 paper, 2017). The most malignant astrocytic tumor (WHO grade IV). "Another interesting observation is theelevated expression of NAT2 detected in our glioblastoma culture:since this overexpression has not yet been reported for glioblastomas, it may proveto be a potential new therapeutic target." (PMID 28522553, 2017).
glioma (1 paper, 2015). A benign or malignant brain and spinal cord tumor that arises from glial cells (astrocytes, oligodendrocytes, ependymal cells). "Increased expression of each of NAT1, NAT2 and NAT10 correlated negatively with patient survival in the group of “all gliomas” patients." (PMID 26292663, 2015).
Glucose intolerance (1 paper, 2016). Glucose intolerance (GI) can be defined as dysglycemia that comprises both prediabetes and diabetes. "Treatment with NAT-1 and NAT-2 reduced the glucose intolerance as is evident from the AUC of the OGTT curve, the activity of NAT-1 being comparable to that of the standard drug metformin." (PMID 27790148, 2016).
head and neck cancer (1 paper, 2021). A primary or metastatic malignant neoplasm affecting the head and neck. "Background and objective:N-acetyltransferases 1 and 2 (NAT1 and NAT2) genes have polymorphisms in accordance with slow and rapid acetylator phenotypes with a role in the development of head and neck cancers (HNCs)." (PMID 34684132, 2021).
Impaired glucose tolerance (1 paper, 2014). An abnormal resistance to glucose, i.e., a reduction in the ability to maintain glucose levels in the blood stream within normal limits following oral or intravenous administration of glucose. "NAT2 may improve the screening properties of SF in predicting the risk of complications or impaired glucose tolerance." (PMID 24934506, 2014).
Infertility (1 paper, 2022). "This study examined the association of smoking with ovarian reserve in a cross-sectional study of 207 women enrolled in the Louisville Tobacco Smoke Exposure, Genetic Susceptibility, and Infertility (LOUSSI) Study and assessed effect modification by NAT2 acetylator phenotype." (PMID 36512605, 2022).
intrahepatic cholangiocarcinoma (1 paper, 2012). A carcinoma that arises from the intrahepatic bile duct epithelium in any site of the intrahepatic biliary tree. "Altered expression of drug metabolizing enzymes, such as UGT1A, UGT2B, SULT1C, NAT2 and GSTO have been reportedly associated with intrahepatic cholangiocarcinoma in endemic area of liver fluke infection." (PMID 22514698, 2012).
Klebsiella pneumonia (1 paper, 2014). An pneumonia caused by infection with Klebsiella. "Similar difference have also been observed with NAT from Klebsiella pneumonia, where NAT activity on 2-aminoflurane (substrate for NAT1 and NAT2) was found to higher as compared to PABA, which is known to be a specific substrate for NAT1." (PMID 26034680, 2014).
larynx cancer (1 paper, 2013). A primary or metastatic malignant neoplasm involving the larynx. "In a recent study on the Turkish population, the slow acetylator NAT2*7 allele was correlated to a reduced UADT cancer risk as well as larynx cancer, thus suggesting a protective role of NAT2*7 genotype in HNC." (PMID 24151610, 2013).
malaria (1 paper, 2009). Malaria is a serious and sometimes fatal disease caused by a parasite that commonly infects a certain type of mosquito which feeds on humans. "Agreement between results obtained from sequencing and from the microarray on 18 SNPs within eight cyp isoenzyme genes and nat2 genes from 26 Cambodian and 70 Tanzanian malaria patients was tested." (PMID 20003204, 2009).
male infertility (1 paper, 2021). The inability of the male to effect fertilization of an ovum after a specified period of unprotected intercourse. "Meanwhile, NAT2 participates in the detoxification of toxic arylamines, aromatic amines and hydrazines, and it is a novel genetic marker for susceptibility to idiopathic male infertility." (PMID 34686208, 2021).
myopia (1 paper, 2025). "Our findings established an association between myopia pathogenesis and NAT2, an enzyme involved in mitochondrial metabolism." (PMID 41169617, 2025). "The genome-wide association study analysis was performed for axial length of eyes in a Chinese population aged 4 to 18 years (n = 6,345), and the most significant locus was 8p22, with NAT2 identified as a potential risk-associated gene for myopia." (PMID 41169617, 2025). "The study was to explore risk-associated genes of myopia and identified that N-acetyltransferase 2 (NAT2) acted as a regulator in the pathological process of myopia." (PMID 41169617, 2025). "NAT2 was down-regulated by hypoxia in form deprivation-induced murine myopia, and the adeno-associated virus-induced genetic intervention of NAT2 in sclera influenced myopia progression." (PMID 41169617, 2025). "This study identified NAT2 as a risk-associated gene for myopia through GWAS analysis of AL in a youth population." (PMID 41169617, 2025). "In FDM mice, αKG treatment suppressed myopia development and reversed the detrimental effect of NAT2 deficiency on myopia." (PMID 41169617, 2025). "In conclusion, NAT2 represents a newly identified risk-associated gene of myopia, serving as a key regulator of disease progression." (PMID 41169617, 2025). "The findings suggested that low expression of NAT2 was associated with formation of myopia." (PMID 41169617, 2025). "Additionally, given that myopia is a polygenic disorder, it is essential to explore potential genetic interactions between NAT2 and other established myopia-associated genes." (PMID 41169617, 2025). "Considering these results and given that NAT2 is a regulator for several pathophysiological processes associated with myopia, we proposed that low expression of NAT2 was correlated with long AL and, thus, a potential risk for myopia." (PMID 41169617, 2025). "Thus, the present study aims to validate NAT2 as a myopia risk-associated gene and delves into its impact on scleral fibroblasts in myopia probably by regulating mitochondrial metabolism, which will provide novel insights and therapeutic avenues for the management of myopia." (PMID 41169617, 2025). "Both genetic manipulation of NAT2 and αKG supplementation demonstrate therapeutic potential in experimental myopia, offering novel strategies for disease prevention and treatment." (PMID 41169617, 2025). "Since scleral hypoxia is a critical precipitating factor for myopia, we further performed hypoxia simulation on scleral fibroblasts to simulate the pathological microenvironment of myopia and found a decrease in the expression of NAT2." (PMID 41169617, 2025). "Although this study has made important progress in revealing the role of NAT2 in myopia, certain limitations should be acknowledged." (PMID 41169617, 2025). "To clarify the mechanism under the influence of NAT2 on myopia, we conducted RNA sequencing of sclera from FDM mice injected with AAV and the mRNA expression was compared (AAV-shNat2 versus AAV-shCon)." (PMID 41169617, 2025). "In the current study, we verified the effect of αKG on myopia, which is a downstream metabolite of NAT2 and a common dietary nutritional supplement." (PMID 41169617, 2025). "On the contrary, AAV-Nat2 administration significantly promoted the expression of NAT2 in sclera and suppressed the development of myopia." (PMID 41169617, 2025). "Our ongoing GWAS, focusing on AL in a youth cohort, has implicated N-acetyltransferase 2 (NAT2), a vital metabolic enzyme, as a potential modulator of myopia progression." (PMID 41169617, 2025). "To verify the effect of NAT2 on myopia development, we designed AAV8 to alter the expression of NAT2 in murine sclera." (PMID 41169617, 2025). "Subsequent experimental validation confirmed the HIF-1α-induced down-regulation of NAT2 in myopic sclera and demonstrated that genetic modulation of NAT2 expression in murine sclera directly influenced myopia progression." (PMID 41169617, 2025).
myopia (continued). "In the current study, we found the novel AL-related gene NAT2 and verified its role in regulating myopia progression." (PMID 41169617, 2025). "Whether NAT2 expression in these tissues contributes to myopia pathogenesis warrants further investigation." (PMID 41169617, 2025). "The findings indicated that NAT2 acted as a regulator in myopia progression and might be a potential therapeutic target for myopia." (PMID 41169617, 2025). "The findings indicated the role of NAT2 in regulating scleral structure in myopia." (PMID 41169617, 2025). "Importantly, we identified αKG supplementation as a potential therapeutic strategy, providing a theoretical foundation for novel myopia interventions targeting NAT2 and mitochondrial metabolism." (PMID 41169617, 2025). "In summary, genetic inhibition of NAT2 induced myopia, while up-regulation of NAT2 attenuated it." (PMID 41169617, 2025). "Additionally, administration with α-ketoglutarate, a downstream metabolite of NAT2, effectively suppressed myopia progression in murine models." (PMID 41169617, 2025). "Since the phenotype of fibroblasts is closely related to the synthesis and degradation of ECM, NAT2 might have effects on myopia by regulating phenotypic transition of fibroblasts and ECM remodeling in sclera, which are crucial processes in the pathogenesis of myopia." (PMID 41169617, 2025). "We explored whether NAT2 knockdown in sclera could induce myopia in mice." (PMID 41169617, 2025). "Overall, these findings illustrated that NAT2 was the direct trans-repression target of HIF-1α in scleral fibroblasts under hypoxia, which suggested the mechanism that NAT2 was down-regulated in myopia." (PMID 41169617, 2025). "Taken together, these findings illustrated that NAT2 regulated phenotypic transition of scleral fibroblasts and scleral ECM remodeling in myopia." (PMID 41169617, 2025). "Along with the down-regulation of NAT2, there was an increase in the expression of hypoxia inducible factor-1α (HIF-1α) in myopic sclera, which was reported as a crucial transcription factor in hypoxic response and involved in myopia pathogenesis." (PMID 41169617, 2025). "Collectively, these results indicated that NAT2 might mediate crosstalk between scleral ECM and choroidal vascular function in myopia, potentially through the regulation of TGF-β secretion." (PMID 41169617, 2025). "To further identify the relationship of NAT2 and myopia, we measured the expression of NAT2 in murine eyes with form deprivation-induced myopia (FDM), compared with those without form deprivation." (PMID 41169617, 2025). "Given that TGF-βs are key regulators of vascular function and choroidal vascular dysfunction is a well-established contributor to myopia pathogenesis, we sought to investigate whether ECM derived from NAT2-altered scleral fibroblasts could influence choroidal vascular function." (PMID 41169617, 2025).
palate clefts (1 paper, 2019). "In humans, deficiency in folates, in which NAT1 is implicated, is often associated with many congenital malformations including palate clefts, and some mutations in both NAT1 and NAT2 have been associated with this condition." (PMID 31068377, 2019).
polyneuropathy (1 paper, 2014). A disease or disorder affecting more than one nerve. "This was demonstrated in 1960 when the earliest pharmacogenomic association of polyneuropathy with slow acetylation of isoniazid by N-acetyltransferase-2 (NAT2) was reported." (PMID 25181945, 2014).
psoriasis vulgaris (1 paper, 2018). Plaque psoriasis is the most common presentation of psoriasis. "In our study, the genotype and allele frequencies of three polymorphisms of the NAT2 gene (481C>T, 590G>A, and 857G>A) were compared between psoriasis vulgaris patients and controls." (PMID 29992137, 2018). "Three polymorphisms (rs1799929, rs1799930, and rs1799931) in NAT2 gene were genotyped and compared by real-time PCR method in 260 psoriasis vulgaris patients and 200 healthy controls." (PMID 29992137, 2018). "Firstly, NAT2 polymorphisms were evaluated for having an effect on the onset age of psoriasis vulgaris." (PMID 29992137, 2018). "However, to the best of our knowledge, there are only two studies on the association of NAT2 gene variants with psoriasis vulgaris." (PMID 29992137, 2018). "Secondly, we assessed whether NAT2 polymorphisms were associated with the severity of psoriasis vulgaris." (PMID 29992137, 2018). "With this hypothesis, our goals were (i) to investigate whether the NAT2 gene polymorphisms are related to development of psoriasis vulgaris (ii) and to detect whether the NAT2 gene polymorphisms have an impact on the clinical features of psoriasis vulgaris such as age of onset and severity." (PMID 29992137, 2018). "We, therefore, think that the relationship between certain SNPs and the clinical features of the psoriasis vulgaris is directly related to the NAT2 itself, rather than to linkage disequilibrium between these alleles and functional polymorphisms." (PMID 29992137, 2018).
pulmonary embolism (1 paper, 2022). The obstruction of the pulmonary artery or one of its branches by an embolus, sometimes associated with infarction of the lung. "By comparing the resulting differentially expressed genes with six genes encoding blood metabolites, LIPC and NAT2 were found to be differentially expressed in association with pulmonary embolism." (PMID 36038828, 2022). "Finally, we compared the six blood metabolite genes obtained with the differentially expressed genes of pulmonary embolism and found that LiPC and NAT2 were differentially expressed in patients with pulmonary embolism when compared to the normal healthy population." (PMID 36038828, 2022).